PTPA (protein phosphatase 2 phosphatase activator)
Description:
PPIases accelerate the folding of proteins. It catalyzes the cis-trans isomerization of proline imidic peptide bonds in oligopeptides (By similarity). Acts as a regulatory subunit for serine/threonine-protein phosphatase 2A (PP2A). Modulates PP2A activity or substrate specificity, probably by inducing a conformational change in the catalytic subunit, a proposed direct target of the PPIase. Can reactivate inactive phosphatase PP2A-phosphatase methylesterase complexes (PP2A(i)) in presence of ATP and Mg(2+) (By similarity). Reversibly stimulates the variable phosphotyrosyl phosphatase activity of PP2A core heterodimer PP2A(D) in presence of ATP and Mg(2+) (in vitro). The phosphotyrosyl phosphatase activity is dependent of an ATPase activity of the PP2A(D):PPP2R4 complex. Is involved in apoptosis; the function appears to be independent from PP2A.
Synonyms: PPP2R4; PR53; PARK25; PP2A
Tractability: Small molecule: a structure with a bound ligand is known; it has a binding pocket of medium quality. PROTAC: ubiquitination databases record sites on it; a small molecule that binds it is known.
Target class: Protein phosphatase regulatory subunit; Phosphatase; Enzyme; Protein Phosphatase
Gene: Protein-coding gene on chromosome 9 (129,110,550 to 129,148,946, forward strand). Ensembl gene ENSG00000119383.
Subcellular location: Cytoplasm; Nucleus
Subcellular location (Human Protein Atlas): Nucleoplasm; Cytosol
Gene Ontology:
Molecular function: ATP binding; phosphatase binding; phosphoprotein phosphatase activity; protein binding; protein homodimerization activity; protein phosphatase 2A binding; protein phosphatase regulator activity; protein tyrosine phosphatase activator activity; signaling receptor binding; peptidyl-prolyl cis-trans isomerase activity; phosphatase activator activity
Biological process: positive regulation of apoptotic process; mitotic spindle organization
Cellular component: ATPase complex; calcium channel complex; cytoplasm; cytosol; extracellular exosome; nucleoplasm; nucleus; protein phosphatase type 2A complex
Genetic constraint (gnomAD): Loss-of-function variants: 12 observed, 36.65 expected, observed/expected ratio (o/e) 0.33, 90% interval 0.21 to 0.53. The upper end of that interval is the gene's LOEUF score, 0.53, which puts it in group 2 of 6, group 1 being the genes least tolerant of losing a copy. Missense variants: 301 observed, 367.02 expected, observed/expected ratio (o/e) 0.82, 90% interval 0.75 to 0.9. Synonymous variants: 151 observed, 140.02 expected, observed/expected ratio (o/e) 1.08, 90% interval 0.94 to 1.23.
Homologues: Orthologues: chimpanzee PTPA (100% identical), mouse Ptpa (96% identical), guinea pig PTPA (94% identical), macaque PTPA (93% identical), dog PTPA (92% identical), rat Ptpa (89% identical), tropical clawed frog ptpa (84% identical), rabbit PTPA (83% identical), pig PTPA (82% identical), zebrafish ptpa (82% identical), Drosophila melanogaster Ptpa (46% identical), Caenorhabditis elegans Y71H2AM.20 (44% identical), and 2 more.
Diseases named in the same sentence as PTPA in open-access papers:
PTPA is named in the same sentence as 299 diseases in open-access papers, as found by Europe PMC text mining. Sharing a sentence is not in itself a finding about the gene and the disease. The quoted sentences say what the papers report.
breast carcinoma (90 papers, 2009 to 2025). "So, CUG2, E2F8, RAE1, and PTPA might not be the downstream targets of MBNL1-AS1 in breast cancer cells." (PMID 35518784, 2022).
lung carcinoma (58 papers, 2009 to 2026). "Thus, we speculate that PtpA might potentially contribute to lung cancer development during chronic Mtb infection through regulating the transcription of certain checkpoint protein-coding genes (such as GADD45A) and ncRNAs." (PMID 28811474, 2017).
Alzheimer disease (56 papers, 2011 to 2026). A progressive, neurodegenerative disease characterized by loss of function and death of nerve cells in several areas of the brain leading to loss of cognitive function such as memory and language. "PTPA is decreased in the brains of Alzheimer’s disease (AD) mouse models." (PMID 37383425, 2023).
gastric cancer (19 papers, 2016 to 2025). A primary or metastatic malignant neoplasm involving the stomach. "With the help of univariate cox regression analysis, we found that six lncRNAs, lnc-SLC26A11, lnc-CHAF1B-3, lnc-CHAF1B-2, LINC00106, MIR3142HG and lnc-PTPA-3 had significant correlation with prognosis in gastric cancer." (PMID 34760687, 2021). "Taken together, the immune-related lncRNA signature was established with lnc-SLC26A11, lnc-CHAF1B and lnc-PTPA attributing to its prominent prognosis predictive potential in gastric cancer." (PMID 34760687, 2021).
asthma (17 papers, 2011 to 2025). "With respect to increased risk of asthma, blood genes again had the largest relative effect sizes in males (BAG6, CCNG, CRAT, PTPA, and FAM89B), with female training genes exhibiting the largest effects in ATP6V1G2 in the vastus lateralis, ENDOU in white adipose, and CCNF in blood." (PMID 38693125, 2024).
Parkinson disease (15 papers, 2012 to 2026). A progressive degenerative disorder of the central nervous system characterized by loss of dopamine producing neurons in the substantia nigra and the presence of Lewy bodies in the substantia nigra and locus coeruleus. "PTPA deficiency leads to the accumulation of inactive PP2A and has been described in two families showing intellectual disability and very early-onset neurodevelopmental delay, followed two decades later by parkinsonism responsive to levodopa." (PMID 41179085, 2025). "Moreover, several PTPA variants that impair activation of PP2A were recently reported to be linked to early onset parkinsonism with intellectual disability." (PMID 37991902, 2024). "In the cases of PTPA (PPP2R4)-related intellectual disability, the late phenotype is characterized by early-onset dopa-responsive (adolescence) Parkinson's disease." (PMID 41179085, 2025).
tuberculosis (5 papers, 2016 to 2026). A chronic, recurrent infection caused by the bacterium Mycobacterium tuberculosis. "This review synthesizes current knowledge on the characteristics, functions, and potential inhibitors of PtpA, underscoring its significance as a therapeutic target in the ongoing battle against tuberculosis and its associated challenges." (PMID 41601639, 2026). "With the increasing understanding of the specific mechanisms involved, numerous studies have suggested that developing inhibitors that specifically target PtpA is a promising strategy for combating tuberculosis." (PMID 41601639, 2026). "Mycobacterium tuberculosis (Mtb) protein tyrosine phosphatase A (PtpA) is a crucial tyrosine phosphatase involved in the pathogenesis of tuberculosis." (PMID 41601639, 2026). "Undoubtedly, the development of new drugs targeting PtpA represents a key breakthrough in the fight against drug-resistant tuberculosis." (PMID 41601639, 2026). "Before assessing the feasibility of its inhibitors for treating tuberculosis, it is essential to clearly understand the specific primary pathways that PtpA influences in host cells." (PMID 41601639, 2026). "This review will integrate knowledge on the structure and function of PtpA, focusing on its potential as a drug target in addressing the growing challenge of tuberculosis." (PMID 41601639, 2026). "With an increasing understanding of PtpA’s functions, inhibitors targeting it to combat tuberculosis have gradually emerged." (PMID 41601639, 2026). "Inhibition of PtpA remarkably attenuates M. tuberculosis growth in human macrophages; therefore, Mt PtpA is a target for developing anti-tuberculosis drugs." (PMID 37623723, 2023).
iron deficiency (3 papers, 2016 to 2025). "Our prior work identified iron depletion as a novel exogenous stressor triggering spontaneous bradyzoite conversion, with the phosphotyrosyl phosphatase activator (PTPA) protein emerging as a critical mediator of iron deficiency-induced differentiation." (PMID 40498010, 2025).
rheumatoid arthritis (3 papers, 2019 to 2026). A chronic, systemic autoimmune disorder characterized by inflammation in the synovial membranes and articular surfaces. "This study aimed to assess the presence of PtpA antibodies in the sera of Mexican individuals with rheumatoid arthritis (RA) and investigate its possible use as a biomarker for disease activity." (PMID 39752467, 2025).
cyst (2 papers, 2022 to 2025). A sac-like closed membranous structure that may be empty or contain fluid or amorphous material. "Depleting PTPA impaired tachyzoite proliferation, invasion, and gliding motility, while stress-induced bradyzoites exhibited defective cyst formation and vacuolar swelling." (PMID 40498010, 2025).
spinocerebellar ataxia (2 papers, 2022 to 2025). "The novel PTPA finding agrees with previous work of the role of phosphatase 2A controlling cell growth and division, regulating dendritic spine morphology and whose dysfunction is a known cause of spinocerebellar ataxia." (PMID 35079123, 2022).
Angelman syndrome (1 paper, 2023). A neurogenetic disorder characterized by severe intellectual deficit and distinct facial dysmorphic features. "Low levels of UBE3A decreased the ubiquitination of PTPA, which further accelerated PP2A holoenzyme assembly, and enhanced its activity in angelman syndrome." (PMID 37461021, 2023).
dyslexia (1 paper, 2025). A learning disorder characterized by an impairment in processing written words. "The most significantly associated independent SNPs; rs13082684 (PPP2R3A), rs2426117 (CSE1L) and rs9696811 (located between PTPA and IER5L), were consistent with loci reported in the univariate dyslexia GWAS." (PMID 40825760, 2025).
lung adenoma (1 paper, 2017). A benign, well circumscribed epithelial neoplasm that arises from the bronchus or the lung parenchyma. "Consistently, overexpressed PtpA was also largely co-localized with the nucleus of U937 cells and human lung adenoma A549 cells." (PMID 28811474, 2017). "In addition, PtpA-expressing Mycobacterium bovis Bacillus Calmette-Guerin (BCG) promotes cell proliferation and migration of a human lung adenoma cell line in vitro and in a mouse xenograft model." (PMID 28811474, 2017). "Furthermore, PtpA-expressing Mycobacterium bovis BCG promotes proliferation and migration of human lung adenoma A549 cells in vitro and in a mouse xenograft model." (PMID 28811474, 2017).
primary immunodeficiency (1 paper, 2023). "In the present study, we found that CTG, which encodes leucine, was the most preferred codon in APP, CCND1, and PTPA, as well as in genes common to primary immunodeficiency and cancer." (PMID 37383425, 2023).
skin papilloma (1 paper, 2025). A benign papillary neoplastic growth on the skin composed of epithelial cells and a fibrous stalk. "PTPA encodes for an activator of PP2A, indicating that the overall activity of PP2A B’56γ/ε (and presumably other B56 isoforms) was reduced in favor of tumorigenesis by increasing susceptibility to DMBA/TPA-induced skin papillomas." (PMID 41146310, 2025).
tumor (522 papers, 2006 to 2026). "Together, these results indicate that Mtb effector protein PtpA contributes to Mtb-promoted tumor cell proliferation, migration, and invasion, which are partially dependent on MKI67." (PMID 33097805, 2020). "We then further demonstrated that PtpA contributes to MKI67-mediated tumor cell proliferation, migration, and invasion during Mtb infection." (PMID 33097805, 2020). "BCG ΔPtpA or BCG (ΔPtpA + PtpA Δ1-20) infection significantly decreased the size and weight of the xenograft tumor as compared with that of WT BCG, BCG (ΔPtpA + PtpA) and BCG (ΔPtpA + D126A) groups at 9 and 12 days after injection." (PMID 28811474, 2017). "The expression of Ki-67, a measure for tumor cell proliferation, was increased by PtpA or its phosphatase-inactive mutant D126A in xenograft tumors, in comparison with the truncated PtpA (PtpA Δ1-20)." (PMID 28811474, 2017). "Interestingly, according to our previous findings, MKI67 is a potential host gene regulated by Mtb PtpA, a key effector protein that can enter into the host cell nucleus and regulate cell proliferation and migration to promote tumor development." (PMID 33097805, 2020). "Moreover, PTPA-deficient mice had significantly impaired PP2A activity, decreased methylation, and spontaneously developed tumours." (PMID 30104481, 2018). "Phosphotyrosyl phosphatase activator (PTPA/PP2A), a member of the serine/threonine protein phosphatase family, is a tumor suppressor gene product." (PMID 37383425, 2023). "To investigate the potential regulatory function of PtpA in tumor progression in vivo, we used a mouse xenograft model using A549 cells infected with WT BCG, BCG (ΔPtpA + PtpA), BCG ΔPtpA, BCG (ΔPtpA + D126A), or BCG (ΔPtpA + PtpA Δ1-20) strain." (PMID 28811474, 2017). "Furthermore, tumor tissues were embedded in paraffin and further analyzed with hematoxylin-eosin staining and immunohistochemistry staining to detect the levels of Ki-67 and PtpA, and the bacterial load in homogenates of tumors was calculated to examine the survival of BCG in the mice." (PMID 28811474, 2017). "Moreover PtpA, a significant effector protein that can enter the nucleus of the host cell and control cell migration and proliferation to encourage tumor growth, seems to support MKI67-mediated tumor cell invasion, migration, and proliferation during M. tuberculosis infection." (PMID 36674038, 2023).
cancer (455 papers, 2006 to 2026). A tumor composed of atypical neoplastic, often pleomorphic cells that invade other tissues. "Present study has unavoidable limitation of using four genes APP, CCND1, CCNE1, and PTPA only, since so far only four genes have been identified those are commonly implicated in cancer and neurodegeneration." (PMID 37383425, 2023). "Studies also showed that 70% of cancer patients have a heterozygous deletion or a missense mutation in PPP2R4, the gene for PTPA, the cellular PP2A activator." (PMID 38184584, 2024). "APP, Cyclin D, and Cyclin E are simultaneously up-regulated in cancer and neurodegeneration, and PTPA tended to be down-regulated." (PMID 37383425, 2023). "Cyclins D and E have been reported to be up-regulated, whereas PTPA has been reported to be down-regulated in cancer and neurodegenerative disease [reviewed in]." (PMID 37383425, 2023). "PP2A activity is further regulated by several endogenous inhibitors (e.g., KIAA1524/CIP2A, SET), the expression of which is often increased in cancer cells, and by cellular activators (e.g., PTPA), the expression of which is often decreased in tumors." (PMID 37170215, 2023). "Here, the authors show that PtpA also enters the nucleus, affects the expression of several host genes, and promotes proliferation and migration of a cancer cell line." (PMID 28811474, 2017). "Similarly, PP2A inactivation via PPP2R4 (PTPA) haploinsufficiency leads to a worse prognosis in many cancer types, including endometrial carcinosarcomas." (PMID 31214504, 2019). "In cancer and neurodegeneration, APP, Cyclin D, and Cyclin E are up-regulated, whereas PTPA is down-regulated." (PMID 37383425, 2023).
infection (51 papers, 2008 to 2026). The state of being infected such as from the introduction of a foreign agent such as serum, vaccine, antigenic substance or organism. "For example, the Staphylococcus aureus LMW-PTP, PtpA, is secreted during macrophage infection and interacts with the cytoskeletal associated protein, coronin-1A." (PMID 34015051, 2021). "Mycobacteria are known to secrete low-molecular-weight tyrosine phosphatases during infection, particularly protein tyrosine phosphatase A (PtpA), which exhibits both tyrosine phosphatase activity and non-enzymatic functions." (PMID 41601639, 2026). "It has been identified that PtpA from M. paratuberculosis possesses similar dephosphorylating activity and a secretory effect as seen in Mtb and is a crucial protein for infection detection." (PMID 41601639, 2026). "The discovery that BafA1’s antimicrobial activity depends on PtpA means that BafA1 should be cautiously considered a probe of vesicular acidification in infection models." (PMID 41170946, 2025). "We found that BafA1 binds to PtpA and amplifies the toxic effect of Mtb intracellular infection, whereas ClaB possesses prodrug-like qualities that result in reduced heavy metal tolerance in bacteria." (PMID 41170946, 2025). "To further investigate the regulatory role of PtpA in ferroptosis during Mtb infection, we deleted the gene encoding ptpA in Mtb H37Rv (Mtb ΔptpA) and complemented Mtb ΔptpA with WT ptpA (Mtb ΔptpA:ptpA) for infection of U937 cells." (PMID 36932056, 2023). "During infection, U937 cells infected with WT Mtb or Mtb ΔptpA:ptpA strain showed less resistance to ferroptosis accompanied by elevated LDH release and accumulation of lipid peroxides, compared with cells infected with Mtb ΔptpA strain." (PMID 36932056, 2023). "PtpA is a secreted protein during infection; thus, it constitutes an ideal target for drug design as the drugs would not need to cross the mycobacterial envelope, a barrier that explains much of the resistance of Mtb to antibiotics." (PMID 37424790, 2023). "Our findings suggest that PtpA is required for a global deSUMOylation in host cells, at least at a later stage of infection (i.e., 24-h pGt), by lowering the level of Ubc9 to promote its intracellular survival." (PMID 37819153, 2023). "We have previously shown that PtpA is released during growth and macrophage infection, and that deletion of ptpA reduces S. aureus intramacrophage survival and infectivity." (PMID 37819153, 2023). "PtpA inhibitors lack direct antimicrobial activity in broth culture yet are able to facilitate infection clearance." (PMID 33826491, 2021). "The mycobacterial protein phosphatase PtpA was secreted within macrophages upon infection with MAP and Mtb." (PMID 32635236, 2020). "Results indicated that PtpA (in green) co-localized at 24 h and 48 h post-infection with MAP (in red), suggesting that MAP used similar PtpA secretion mechanisms in moDCs, as in the MAP and Mtb-infected macrophage." (PMID 32635236, 2020). "To conclude, our studies established a central role for PtkA in macrophage infection by Mtb and correlated the enzyme activity to phosphorylation and secretion of TrxB2 and PtpA." (PMID 29317718, 2018). "We also conducted a time course analysis for intracellular localization of PtpA, and observed that the nuclear localization of PtpA increased over time within 6 h post-infection." (PMID 28811474, 2017). "With respect to how PtpA activity is regulated during infection, we think that in view of our results and our hypothesis, more studies must be carried out to understand the potential regulatory role of ubiquitin and other relevant molecules as fatty acids." (PMID 37424790, 2023). "The PtpA nuclear localization, could contribute to explain the observed 10-fold decrease in the hTFPα mRNA observed during the infection with the virulent Mtb H37Rv." (PMID 37424790, 2023).